ACTL6A (actin like 6A)
Diseases named in the same sentence as ACTL6A in open-access papers (continued):
Sharing a sentence is not in itself a finding about the gene and the disease.
ovarian carcinoma (10 papers, 2011 to 2025). A malignant neoplasm originating from the surface ovarian epithelium. "In contrast, depleting ACTL6A hampers the repair of DNA damage caused by cisplatin, thereby making platinum-resistant ovarian cancer cells more sensitive to the drug." (PMID 40657395, 2025). "The ACTL6A gene is frequently amplified in cancers, such as lung and ovarian cancer, and ACTL6A overexpression has been linked to an earlier relapse rate in ovarian and lung cancer patients who received cisplatin therapy." (PMID 38256203, 2024). "We have taken the list of ACTL6A-correlated genes associated with ovarian cancer pathway from KEGG database." (PMID 36768349, 2023). "The LinkFinder module of LinkedOmics was showed the association genes of ACTL6A based on the data of 303 ovarian cancer patients." (PMID 36768349, 2023). "Considering both OS and PFS, the survival analysis demonstrated that high expression levels of ACTL6A was associated with a poor prognosis of ovarian cancer patients (p < 0.001 for OS and PFS), as well as in ovarian cancer patients received chemotherapy (p = 0.031 for OS and p = 0.0021 for PFS)." (PMID 36768349, 2023). "Therefore, our results provide a molecular mechanism underlying antitumor activity by targeting ACTL6A and lay a foundation to improve the clinical outcome of ovarian cancer patients." (PMID 31649264, 2019). "Building upon its prometastatic roles in CRC, ACTL6A also exhibits significant pro-invasive and chemoresistant properties in ovarian cancer." (PMID 40657395, 2025). "Collectively, these findings establish ACTL6A as a dual-functional target for both prognostic assessment and precision therapy in ovarian cancer." (PMID 40657395, 2025). "The findings clarify the role of ACTL6A in metabolic reprogramming in ovarian cancer and propose a potential molecular mechanism for targeting ACTL6A to inhibit glycolysis and exert anti-tumor activity." (PMID 40657395, 2025). "Phosphoglycerate kinase 1(PGK1) expression can be upregulated by overexpressing ACTL6A, but PGK1 expression is downregulated by ACTL6A knockdown, which impacts the glycolysis and growth of ovarian cancer cells." (PMID 40755753, 2025). "Recent studies revealed that follicle-stimulating hormone (FSH)-stimulated glycolysis in ovarian malignancy comprised a higher level of the poor prognostic factor ACTL6A, which forecasted metastasis and prognosis of ovarian cancer patients." (PMID 38645487, 2024). "Unlike most of the published reports showing that several surface markers used to identify ovarian CSCs, such as CD24, CD44, CD117, and CD133, we have unveiled the ACTL6A had poor prognosis and correlated enrichment of CSCs in ovarian cancer." (PMID 36768349, 2023). "Our study found the relationship of ACTL6A and the advanced ovarian cancer cells in chemoresistance, metastasis, poor prognosis, and CSCs." (PMID 36768349, 2023). "ACTL6A expression elevated within the chemoresistance and metastasis of ovarian cancer and cancer stem-like cells." (PMID 36768349, 2023). "The 15 ovarian cancer cells with high ACTL6A expression had low log (IC50) values in an optimal response to CP734714." (PMID 36768349, 2023). "In this study, we proposed that the common gene, ACTL6A, was selected from the datasets of features of the ovarian cancer stem-like cell made by Venn diagram approaches, and it was positively correlated with cell cycle progression." (PMID 36768349, 2023). "Previous research demonstrated that follicle-stimulating hormone (FSH)-enhanced glycolysis in ovarian cancer contained a high level of ACTL6A and that ACTL6A increased phosphoglycerate kinase 1 (PGK1), therefore aiding the proliferation of ovarian cancer." (PMID 36768349, 2023). "Overall, the present study indicated that the expression of marker of ACTL6A as a poor prognostic factor predicted metastasis and prognosis of ovarian cancer patients." (PMID 36768349, 2023).
ovarian carcinoma (continued). "It is noteworthy that the presentation reveals CP724714 as a potential therapeutic treatment for ovarian cancer in the presence of high ACTL6A expression levels." (PMID 36768349, 2023). "Altered ACTL6A expression inhibits the tumorigenicity of ovarian cancer cells in vivo by downregulating PGK1." (PMID 31649264, 2019). "Collectively, our data provide a new mechanism for tumorigenicity of ACTL6A and reveal a previously unappreciated role for FSH/ACTL6A/PGK1 axis facilitates glycolysis in ovarian cancer." (PMID 31649264, 2019). "Our analysis of genomic profiling of several cancer types in TCGA demonstrated that ACTL6A gene is amplified in 26.73% of ovarian cancer and the amplification is the most common genetic event of ACTL6A in ovarian cancer." (PMID 31649264, 2019). "We identified the critical roles of ACTL6A and PGK1 expression in glycolysis in ovarian cancer and the novel function for ACTL6A in FSH-induced glycolysis." (PMID 31649264, 2019). "Silencing of ACTL6A in vitro inhibits proliferation, clonal growth, and migration, and decreases glucose utilization, lactate production, and pyruvate levels of ovarian cancer cells." (PMID 31649264, 2019). "ACTL6A was amplified in lung squamous cell carcinoma (44.42%), cervical cancer (19.03%), esophageal carcinoma (22.58%), head and neck cancer (20.19%), and ovarian cancer (26.73%)." (PMID 31504061, 2019). "Western blotting analysis showed that stimulation of FSH enhanced PGK1 expression in ovarian cancer cells, which was further eliminated by downregulation of ACTL6A." (PMID 31649264, 2019). "In the current work, we uncover a unique role of ACTL6A that regulates glycolysis in ovarian cancer." (PMID 31649264, 2019). "The genomic and expression profiling of ACTL6A in ovarian cancer has been determined based on TCGA data analysis and IHC detection." (PMID 31649264, 2019). "Our study further reveals that silencing of ACTL6A attenuates FSH-driven ovarian cancer glycolysis by downregulating PGK1 expression." (PMID 31649264, 2019). "We first investigated the effect of ACTL6A on ovarian cancer cell proliferation by MTT and colony-formation assay." (PMID 31649264, 2019). "Oncomine database revealed that ACTL6A is more highly expressed in ovarian cancer tissues than in ovarian surface epithelium or peritoneum tissues." (PMID 31649264, 2019). "Taken together, our findings highlight the critical role of ACTL6A in ovarian cancer development and identify its contribution to glucose metabolism of cancer cells." (PMID 31649264, 2019). "ACTL6A is overexpressed in ovarian cancer, according to Zhang and colleagues." (PMID 40755753, 2025). "ACTL6A has been identified as a key regulator of glycolysis in ovarian cancer." (PMID 40657395, 2025). "On a pre-clinical level, an association between the overexpression of ACTL6A and cisplatin resistance has been observed in lung and ovarian cancer cell lines and lung cancer xenografts, which has been explained by increased repair of cisplatin DNA adducts mediated by ACTL6A." (PMID 38256203, 2024). "Furthermore, it is noteworthy that ACTL6A expression was up-regulated in ovarian cancer sphere cells." (PMID 36768349, 2023). "CP724714 was in the modulation of ACTL6A may serve as a potential novel therapeutic strategy for ovarian cancer." (PMID 36768349, 2023). "More evidence needs to be validated, this result could support the development of the precision medicine for ovarian cancer based on high ACTL6A expression levels." (PMID 36768349, 2023). "ACTL6A was considered to be a novel prognostic marker for ovarian cancer." (PMID 36768349, 2023). "CP724714, a human epidermal growth factor receptor 2 (HER2) inhibitor, could serve as a therapeutic option when ACTL6A levels are high in ovarian cancer cells." (PMID 36768349, 2023). "However, the role of ACTL6A and ACTL6A-related mechanisms in advanced ovarian cancer remains poorly understood." (PMID 36768349, 2023).
ovarian carcinoma (continued). "The data above present that ACTL6A regulates glycolysis to promote ovarian cancer." (PMID 31649264, 2019). "Dysregulation of ACTL6A might be a novel carcinogenic process involved in FSH-induced tumorigenesis of ovarian cancer we describe here." (PMID 31649264, 2019). "Thus, the present study provides mechanistic and clinical evidence supporting a model that ACTL6A induces glycolysis in ovarian cancer cells via PGK1." (PMID 31649264, 2019). "Here we found that ACTL6A-mediated glycolysis in ovarian cancer cells via regulation of PGK1." (PMID 31649264, 2019). "Therefore, we employed lentivirus-mediated shRNA to silence endogenous ACTL6A, to establish the role of ACTL6A in ovarian cancer cell phenotypes." (PMID 31649264, 2019). "Nevertheless, the role of ACTL6A in glycolysis and tumorigenicity of ovarian cancer remains unclear." (PMID 31649264, 2019). "Then we performed Transwell migration studies to examine whether ACTL6A affects the cell motility in ovarian cancer." (PMID 31649264, 2019). "In view of PGK1 was the most altered gene, we chose PGK1 as the target gene and try to investigate whether ACTL6A-enhanced glycolysis in ovarian cancer was dependent upon PGK1." (PMID 31649264, 2019). "The high expression of ACTL6A is a poor prognostic factor in ovarian cancer and may serve as an effective biomarker for predicting treatment-refractory, metastasis, and prognosis of patients with ovarian cancer." (PMID 36768349, 2023). "However, the roles of ACTL6A in the development of ovarian cancer and the regulation of cancer glucose metabolism are mostly unknown." (PMID 31649264, 2019). "Importantly, ACTL6A regulates FSH-enhanced glycolysis in ovarian cancer." (PMID 31649264, 2019). "Notably, drug sensitivity prediction modeling uncovered selective inhibitory effects of HER2 inhibitors (e.g., CP724714) against ACTL6A-high ovarian cancer cells, suggesting that targeting receptor tyrosine kinase signaling may overcome ACTL6A-mediated chemoresistance." (PMID 40657395, 2025). "In other words, targeting the ACTL6A-related pathway, especially with ‘cell cycle’ inhibition, suggested the use of HER2 inhibitors to be promising in ovarian cancer." (PMID 36768349, 2023). "Next, we evaluated the relationship between ACTL6A and PGK1 in ovarian cancer tissues by IHC analysis." (PMID 31649264, 2019). "Here we show that ACTL6A is overexpressed in ovarian cancers compared with adjacent non-tumor tissues, and that ACTL6A overexpression correlates with poor prognosis." (PMID 31649264, 2019). "We found a positive correlation between ACTL6A and PGK1 expression in ovarian cancer tissues." (PMID 31649264, 2019). "Following treatment with platelet releasate, SK-OV-3 cells also showed expression changes in genes involved in, anti-autophagy in endometrial and ovarian cancer [KIAA1324/EIG121], as well as transcriptional regulation [ACTL6A], cell cycle[MUS81], cytoskeletal [TPM4] and homeostatic [TPM4] processes." (PMID 22022533, 2011).
gastric cancer (7 papers, 2023 to 2025). A primary or metastatic malignant neoplasm involving the stomach. "Here, the authors 2 find elevated expression of ACTL6A in gastric cancer promotes glutathione synthesis by regulating 3 GCLC expression to suppress ferroptosis." (PMID 37443154, 2023). "ACTL6A increased the mRNA level of GCLC as a cotranscription factor of NRF2, thereby increasing GSH synthesis and promoting the progression of gastric cancer." (PMID 40651948, 2025). "ACTL6A is a common subunit of the SWI/SNF complex, and recent studies have identified that ACTL6A can inhibit ferroptosis in gastric cancer." (PMID 40342423, 2025). "For instance, actin-like 6 A (ACTL6A) promotes GSH synthesis by elevating the expression of the rate-limiting enzyme GCLC, thereby safeguarding gastric cancer cells from ferroptosis." (PMID 39548421, 2024).
squamous cell carcinoma (7 papers, 2019 to 2025). A carcinoma arising from squamous epithelial cells. "This overview includes ACTL6A studies in liver, squamous cell carcinoma, breast, glioblastoma, gastric, colorectal, ovarian, cervical, and other cancers." (PMID 40657395, 2025). "For example, a scaffolding subunit, ACTL6A, was amplified and functioned as an oncogenic driver in squamous cell carcinoma." (PMID 31504061, 2019). "In squamous cell carcinoma (SCC), the BAF subunit actin-like 6a (ACTL6A) is amplified early in the development of SCC." (PMID 38914477, 2024).
lung carcinoma (6 papers, 2018 to 2025). "In a preclinical study, it was shown that the HDACi panobinostat can reverse cisplatin resistance, which was caused by overexpression of ACTL6A in lung cancer cell lines and xenografts." (PMID 38256203, 2024). "Increased cisplatin resistance was also identified in lung cancer cell lines overexpressing actin-like 6A (ACTL6A), which is a component of several complexes implicated in chromatin remodeling, including the NuA4/TIP60 histone acetyltransferase." (PMID 38256203, 2024). "Moreover, E-X PPI2, E-X AS7, and panobinostat (a HDAC inhibitor) have been reported to silence ERCC1 and ACTL6A expressions in melanoma and ovarian/lung cancers, respectively, via in vitro and preclinical experiments." (PMID 40510426, 2025).
cervical cancer (5 papers, 2019 to 2025). A primary or metastatic malignant neoplasm involving the cervix. "Collectively, these findings demonstrate a dual role for ACTL6A in cervical cancer: as a prometastatic effector downstream of miR-216a-3p loss and as a critical node linking epigenetic regulation to YAP oncogenic signaling." (PMID 40657395, 2025). "For example, DNA replication, cell cycle, mismatch repair, Wnt signaling pathway and Hippo signaling pathway were closely associated with the expression of ACTL6A in cervical cancer." (PMID 34395295, 2021). "In summary, the present study showed that overexpression of ACTL6A was significantly associated with malignant behavior of cervical cancer." (PMID 34395295, 2021). "In addition, a recent study revealed that miR-216-3p was decreased expression in cervical cancer and regulated cell malignant behaviors through inhibiting yes-associated protein signaling through regulating actin-like 6A." (PMID 32489325, 2020). "Next, we examined the role of ACTL6A in cervical cancer cell proliferation by using the MTT and colony formation assay." (PMID 34395295, 2021). "We found that the protein level of ACTL6A in cervical cancer tissues was higher than that in adjacent normal tissues." (PMID 34395295, 2021). "In this study, the mRNA expression and protein level of ACTL6A in cervical cancer samples were determined by public database and immunohistochemical (IHC) analysis." (PMID 34395295, 2021). "Correlation analysis also revealed that ACTL6A was positively correlated with these cell cycle regulation genes in clinical samples of cervical cancer from TCGA." (PMID 34395295, 2021). "Gene set enrichment analysis (GSEA) was used to explore the potential mechanism of ACTL6A in regulating tumorigenesis of cervical cancer." (PMID 34395295, 2021). "We suggest that ACTL6A plays an oncogenetic role in the development of cervical cancer and has potential clinical values in targeted therapy." (PMID 34395295, 2021). "Functional assays confirmed that ACTL6A is an oncogene that promotes the proliferation and cell cycle progression of cervical cancer cells in a c-Myc-dependent manner." (PMID 34395295, 2021). "Here, we investigated the correlation between ACTL6A and differentiation genes in cervical cancer samples from TCGA." (PMID 34395295, 2021). "This supports the idea that ACTL6A is a special oncogenic subunit in the SWI/SNF complex in cervical cancer." (PMID 34395295, 2021). "Silencing ACTL6A expression resulted in decreased cervical cancer cell proliferation, colony formation and tumorigenesis in vitro and in vivo." (PMID 34395295, 2021). "Our study suggested that ACTL6A promoted cell proliferation through regulation of cell cycle via c-Myc in cervical cancer." (PMID 34395295, 2021). "In current study, we provide evidence that ACTL6A promotes the proliferation, clone formation and in vivo tumor formation of cervical cancer cells." (PMID 34395295, 2021). "ACTL6A expression was significantly upregulated in various malignant tumor tissues, including cervical cancer, bladder cancer, breast cancer and esophageal cancer." (PMID 34395295, 2021). "Targeting this regulatory circuit may provide innovative therapeutic opportunities for cervical cancer patients with ACTL6A-driven disease." (PMID 40657395, 2025). "In addition, high expression of ACTL6A was positively correlated with various cancer-related processes of cervical cancer mapping in KEGG pathway." (PMID 34395295, 2021). "Here, we reported a significant increase in ACTL6A protein levels in cervical cancer tissues." (PMID 34395295, 2021). "The role of ACTL6A-stimulated c-Myc activity in cervical cancer was demonstrated here." (PMID 34395295, 2021). "Our results reveal the role of ACTL6A in promoting the proliferation of cervical cancer cells and indicate that ACTL6A may be a promising anticancer therapeutic target." (PMID 34395295, 2021). "The results revealed that ACTL6A was markedly upregulated in cervical cancer tissues." (PMID 34395295, 2021).
cervical cancer (continued). "Furthermore, the expressions of S100P, S100A4, KRT7 and TGM2 were also induced by silencing of ACTL6A in cervical cancer cells." (PMID 34395295, 2021). "Moreover, ACTL6A expression in multiple data sets of cervical cancer was significantly higher than that of normal cervix (GES7803, GSE6791, GSE7410, GSE9750)." (PMID 34395295, 2021). "Clinical correlations of ACTL6A protein level in cervical cancer." (PMID 34395295, 2021). "In addition, ACTL6A co-expressed several important genes in the cervical cancer 3q amplicon, including PIK3CA, SOX2 and TP63." (PMID 34395295, 2021). "Then we examined the protein level of ACTL6A in cervical cancer tissue." (PMID 34395295, 2021). "As ACTL6A expression was closely associated with cell cycle according to GSEA, we then investigated whether ACTL6A affects the cell cycle of cervical cancer cells." (PMID 34395295, 2021). "In this study, we focused on the role of ACTL6A in cervical cancer." (PMID 34395295, 2021). "Therefore, inhibition of ACTL6A might be a promising potential therapeutic strategy for cervical cancer." (PMID 34395295, 2021). "However, the pathological role of ACTL6A was remained poorly understood in cervical cancer." (PMID 34395295, 2021). "Compared with the normal cervix, the expression of ACTL6A was higher in CIN and cervical cancer tissues, and the expression of ACTL6A in CIN increased with the rise of the grade (GSE63514)." (PMID 34395295, 2021). "However, the expression pattern and biological role of ACTL6A in cervical cancer have not been reported." (PMID 34395295, 2021).